ZNF461 (zinc finger protein 461)
Description:
May be involved in transcriptional regulation.
Synonyms: GIOT-1; GIOT1; MGC33911; HZF28
Tractability: PROTAC: ubiquitination databases record sites on it.
Gene: Protein-coding gene on chromosome 19 (36,636,618 to 36,666,853, reverse strand). Ensembl gene ENSG00000197808.
Subcellular location: Nucleus
Subcellular location (Human Protein Atlas): Golgi apparatus; Nucleoli; Nucleoplasm
Pathways (Reactome):
Gene expression (Transcription): Generic Transcription Pathway
Gene Ontology:
Molecular function: protein binding; DNA-binding transcription factor activity, RNA polymerase II-specific; RNA polymerase II cis-regulatory region sequence-specific DNA binding; sequence-specific double-stranded DNA binding
Biological process: regulation of transcription by RNA polymerase II; regulation of DNA-templated transcription
Cellular component: nucleus
Genetic constraint (gnomAD): Loss-of-function variants: 8 observed, 12.49 expected, observed/expected ratio (o/e) 0.64, 90% interval 0.38 to 1.16. The upper end of that interval is the gene's LOEUF score, 1.16, which puts it in group 5 of 6, group 1 being the genes least tolerant of losing a copy. Missense variants: 563 observed, 667.59 expected, observed/expected ratio (o/e) 0.84, 90% interval 0.79 to 0.9. Synonymous variants: 174 observed, 216.11 expected, observed/expected ratio (o/e) 0.81, 90% interval 0.71 to 0.91.
Homologues: Orthologues: chimpanzee ZNF461 (100% identical), dog ZNF461 (82% identical), rabbit ZNF461 (79% identical), pig ZNF461 (76% identical). Paralogues in human: ZFP14 (52% identical), ZNF565 (51% identical), ZFP30 (49% identical), ZNF546 (49% identical), ZNF571 (49% identical), ZNF540 (48% identical), ZFP82 (47% identical), ZNF30 (46% identical), ZNF267 (44% identical), ZNF33B (44% identical), ZNF573 (44% identical), ZNF658 (44% identical), and 164 more.
Diseases named in the same sentence as ZNF461 in open-access papers:
ZNF461 is named in the same sentence as 3 diseases in open-access papers, as found by Europe PMC text mining. Sharing a sentence is not in itself a finding about the gene and the disease. The quoted sentences say what the papers report.
herpes simplex infection (1 paper, 2021). "Our study identified DE TFs such as ZNF180, ZNF763, ZNF792, ZNF718, and ZNF461 associated with asthmatic ASM cells and enriched for the herpes simplex infection pathway." (PMID 34257337, 2021).
ZNF461 also shares sentences with these, for which no sentence is quoted: adenoma (1 paper); adrenal cancer (1).